TRDV3 (T cell receptor delta variable 3)
Description:
V region of the variable domain of T cell receptor (TR) delta chain that participates in the antigen recognition. Gamma-delta TRs recognize a variety of self and foreign non-peptide antigens frequently expressed at the epithelial boundaries between the host and external environment, including endogenous lipids presented by MH-like protein CD1D and phosphoantigens presented by butyrophilin-like molecule BTN3A1. Upon antigen recognition induces rapid, innate-like immune responses involved in pathogen clearance and tissue repair. Binding of gamma-delta TR complex to antigen triggers phosphorylation of immunoreceptor tyrosine-based activation motifs (ITAMs) in the CD3 chains by the LCK and FYN kinases, allowing the recruitment, phosphorylation, and activation of ZAP70 that facilitates phosphorylation of the scaffolding proteins LCP2 and LAT. This lead to the formation of a supramolecular signalosome that recruits the phospholipase PLCG1, resulting in calcium mobilization and ERK activation, ultimately leading to T cell expansion and differentiation into effector cells. Gamma-delta TRs are produced through somatic rearrangement of a limited repertoire of variable (V), diversity (D), and joining (J) genes. The potential diversity of gamma-delta TRs is conferred by the unique ability to rearrange (D) genes in tandem and to utilize all three reading frames. The combinatorial diversity is considerably increased by the sequence exonuclease trimming and random nucleotide (N) region additions which occur during the V-(D)-J rearrangements.
Synonyms: hDV103S1
Tractability: Antibody: UniProt places it where antibodies can reach, with high confidence; UniProt predicts a signal peptide or a membrane-spanning region; its Gene Ontology location is reachable by antibodies, with medium confidence.
Gene: T-cell receptor variable (V) gene on chromosome 14 (22,469,041 to 22,469,698, reverse strand). Ensembl gene ENSG00000256590.
Subcellular location: Cell membrane
Gene Ontology:
Biological process: immune response
Cellular component: immunoglobulin complex; plasma membrane
Homologues: Orthologues: chimpanzee TRDV3 (83% identical), macaque TRDV3 (73% identical), dog TRDV3 (70% identical), rabbit TRDV3 (65% identical), mouse Trdv5 (64% identical), rat AC097037.1 (61% identical), tropical clawed frog MGC147231 (16% identical). Paralogues in human: TRAV14DV4 (31% identical), IGKV1OR2-108 (29% identical), IGKV2-28 (29% identical), IGKV2D-28 (29% identical), IGLV7-43 (29% identical), TRDV1 (29% identical), IGKV1-17 (28% identical), IGKV1-33 (28% identical), IGKV1-6 (28% identical), IGKV1D-13 (28% identical), IGKV1D-33 (28% identical), IGKV3D-20 (28% identical), and 81 more.
Diseases named in the same sentence as TRDV3 in open-access papers:
TRDV3 is named in the same sentence as 4 diseases in open-access papers, as found by Europe PMC text mining. Sharing a sentence is not in itself a finding about the gene and the disease. The quoted sentences say what the papers report.
cancer (1 paper, 2023). A tumor composed of atypical neoplastic, often pleomorphic cells that invade other tissues. "Despite the low patient numbers and high heterogeneity regarding tumour types and biopsy locations of this cohort, we confirmed increased TRDV1 and TRDV3 expression in B2MMUT tumours pan-cancer (two-sided linear regression, P = 0.017, adjusted for tumour type and biopsy site)." (PMID 36631610, 2023).
tumour (1 paper, 2023). "Although rare, B2M alterations were also significantly associated with increased expression of TRDV1/TRDV3 loci in this context (two-sided linear regression, P = 2.2 × 10−17, adjusted for tumour type)." (PMID 36631610, 2023). "Moreover, B2MMUT tumours showed overexpression of multiple KIRs, which clustered together with TRDV1 and TRDV3 on the basis of hierarchical clustering." (PMID 36631610, 2023).
TRDV3 also shares sentences with these, for which no sentence is quoted: psoriasis (1 paper); thyroid cancer (1).